RNU6-132P (RNA, U6 small nuclear 132, pseudogene)
Gene: Small nuclear RNA gene on chromosome 15 (89,714,232 to 89,714,338, forward strand). Ensembl gene ENSG00000206590.
Homologues: Orthologues: chimpanzee U6 (98% identical), macaque U6 (96% identical), rabbit U6 (79% identical), dog U6 (72% identical). Paralogues in human: RNU6-1060P (90% identical), RNU6-15P (90% identical), RNU6-558P (90% identical), RNU6-949P (90% identical), RNU6-1011P (89% identical), RNU6-12P (89% identical), RNU6-13P (89% identical), RNU6-166P (89% identical), RNU6-26P (89% identical), RNU6-31P (89% identical), RNU6-32P (89% identical), RNU6-33P (89% identical), and 1287 more.